FOXM1 (forkhead box M1)
Diseases named in the same sentence as FOXM1 in open-access papers (continued):
Sharing a sentence is not in itself a finding about the gene and the disease.
tumor (continued). "In normal colonic mucosa, FOXM1 expression is weak; however strong staining was observed in the matched primary tumours and notably this was more pronounced in the nodal metastases of the same patients." (PMID 30728402, 2019). "High FOXM1 levels were found to be correlated with EOC tumor grade and stage, and to predict poor prognosis and chemoresistance." (PMID 31829231, 2019). "By targeting FoxM1, E2A inhibits β-catenin in cell nuclei and suppresses the tumor-initiating capacity of CRC cells." (PMID 31234887, 2019). "Our findings reveal that FOXM1 is epigenetically regulated by H3K79 methylation modification in both tumor cells and BMDCs." (PMID 30628173, 2019). "Our previous work demonstrated that miR-671-5p serves as a tumor suppressor by targeting Forkhead box protein M1 (FOXM1)-mediated epithelial-to-mesenchymal transition (EMT) in BC." (PMID 31391072, 2019). "FOXM1 is known to initiate mitosis, and FOXM1 inhibition has been shown to retard tumor growth in a model system for the PCS1 subtype." (PMID 31162796, 2019). "Similar to FOXM1 mRNA, FOXM1 protein expression varied across tumor types and showed a broad spectrum of expression." (PMID 30795624, 2019). "We have also elucidatedthe role of hsa-miR-4756-3p in tumour cell function in vivoas well as in vitro, which is related with TGFβ1 and forkhead box protein M1 (FOXM1)." (PMID 31554904, 2019). "We also checked TGFβ1 signal and EMT signal in primary tumours from control, hsa-miR-4756-3p inhibitor, and hsa-miR-4756-3p inhibitor + FOXM1 KO mice." (PMID 31554904, 2019). "The FOXM1 pathway involves both the cell cycle and DNA damage repair ultimately promoting tumor cell proliferation." (PMID 30974831, 2019). "miR-370 targeted FoxM1 functions as a tumor suppressor in LSCC; miR-1290 acts as a novel potential oncomiR in LSCC; miR-1297 mediates PTEN expression and contributes to LSCC cell progression." (PMID 31384171, 2019). "In this study, we documented that E2A suppresses the expression of FoxM1 at the mRNA and protein levels, and we demonstrated that E2A influences tumor-initiating ability in a FoxM1-dependent manner." (PMID 31234887, 2019). "In summary, our findings revealed an important epigenetic modification to FOXM1, which affects its novel tumor‐promoting role in tumor immunity." (PMID 30628173, 2019). "Our data demonstrate a synergic role of HMGA1 and FOXM1 in governing tumor angiogenesis using an in vivo model." (PMID 31311575, 2019). "Previous studies have shown that FOXM1 is overexpressed in a variety of human malignancies, and most of research has focused on tumor cells including HCC." (PMID 30999932, 2019). "Several studies have shown that FoxM1 activates tumor metastasis, mediates drug resistance, and regulates pluripotency-associated genes responsible for maintaining tumor cells in their undifferentiated state." (PMID 31134895, 2019). "In the nucleus, FOXM1 can trigger the expression of several genes that are involved in tumor initiation processes such as angiogenesis, cell proliferation, cellular migration and invasion, and epithelial-mesenchymal transition." (PMID 30978209, 2019). "Future studies should involve a larger cohort of tumour samples with survival data used to validate FOXM1 as a biomarker for drug resistance." (PMID 30728402, 2019). "Nonetheless, in this study, we demonstrated that FoxM1 is a downstream target in mediating E2A’s function as a tumor suppressor gene in CRC." (PMID 31234887, 2019). "Activation of the Ras/Erk pathway leads to the induction of a plethora of downstream effectors, including Foxm1 (forkhead box M1), in various experimental and human tumor types." (PMID 31569678, 2019). "Previous studies revealed the role of increased FOXM1 expression in proliferation, tumor progression and therapeutic resistance." (PMID 31541075, 2019). "FOXM1 is an oncogenic transcription factor and master regulator of tumor progression and metastasis." (PMID 30782607, 2019).
tumor (continued). "Research has suggested that FOXM1 can promote resistance through enhancing DNA damage repair, resistance to apoptosis, elimination of reactive oxygen species (ROS), and influencing tumor stemness." (PMID 30782607, 2019). "Unlike FOXO1, the FOXM1 protein is upregulated by EWS-FLI1 and serves as an oncogenic mediator that results in tumor proliferation; a reduction of FOXM1 protein results in decreased anchorage independent growth." (PMID 31275859, 2019). "For the first time, the potential association between tumour microenvironment and FSCN1 and FOXM1 was identified." (PMID 31783819, 2019). "miR-509-5p, miR-149 and miR-361-5p act as tumor suppressors, directly binding to the FOXM1 promoter and downregulating its expression in human NSCLC." (PMID 30992007, 2019). "Our research aims to identify the role of the epithelial-mesenchymal transition (EMT) related genes FSCN1 and FOXM1 in the tumour microenvironment and assess their prognostic value in ACCs." (PMID 31783819, 2019). "To address these questions, we determined FOXM1 isoform expression in normal and tumor tissues using TOIL GTEx and TCGA RNA-seq datasets from UCSC Xena." (PMID 30795624, 2019). "Downregulation of FOXM1 resulted in a significant increase in E-cadherin and a decrease in N-cadherin expression, promoting tumor cell invasion." (PMID 31835892, 2019). "In this study, we show that FoxM1 is frequently increased in Middle Eastern EOC and associated with high proliferative index (p = 0.0007) and high grade tumor (p = 0.0024)." (PMID 29423068, 2018). "HLRCC tumor cells subsequently rely on ferritin for FOXM1-mediated proliferation: ferritin knockdown ablated FOXM1 and abrogated cell growth." (PMID 28793787, 2018). "In this study, TMAs confirmed the association of high FOXM1 protein levels with TNBC subtype and high tumor grade." (PMID 30572639, 2018). "Our study found that the FoxM1 tumor cells grew at a higher rate than the control groups in all examples." (PMID 30416986, 2018). "First among these is the need to confirm the findings on FOXM1-dependent drug resistance in primary tumor cells." (PMID 30463534, 2018). "FOXM1 is detected primarily in progenitor and regenerating tissues, as well as tumor cells, which are all highly proliferative." (PMID 30208972, 2018). "Tumor size, resected margin, and the FoxM1 expression level were independent prognostic indicators for DFS (all P < 0.05)." (PMID 30580327, 2018). "Meanwhile, FoxM1 linked closely with the expression levels of stem cell markers including Nanog, Sox2, and OCT4 in tumor samples, and also promoted the expression of these stemness-related genes in vitro." (PMID 30416986, 2018). "In vivo studies further demonstrated that PAX8 overexpression restrained tumor angiogenesis and metastasis in nude mice, which was accompanied by increased expression of miR-612 and decreased expression of FOXM1." (PMID 30021604, 2018). "Mechanistically, Spdef directly repressed expression of Foxm1, a key transcription factor required for tumour cell proliferation, and reduced expression of multiple Foxm1 target genes involved in cell cycle progression including Cdc25b, Cyclin B1, Cyclin A2." (PMID 30200227, 2018). "FoxM1 was overexpressed in 33 of 54 (61.1%) HC cases and was significantly correlated to larger tumor size (P = 0.028)." (PMID 29776401, 2018). "The in vivo experiments in nude mice showed knockdown of LOC653786 repressed xenograft tumor growth and FOXM1 expression." (PMID 29552295, 2018). "Overexpression of FoxM1 was correlated with multiple tumor nodules, tumor size > 5 cm, positive lymph node metastasis and advanced TNM stage." (PMID 30580327, 2018). "Through an integrated analysis of software prediction, molecular and functional studies, we identified FOXM1 as a direct downstream target of miR-6868-5p and demonstrated the critical role of miR-6868-5p /FOXM1 axis in the regulation of tumor angiogenesis." (PMID 30486864, 2018).
tumor (continued). "As the important role of FOXM1 in cell proliferation and determination of cell fate, more study is needed to reveal the possible role of FOXM1 in the tumor infiltrating immune cells." (PMID 30208972, 2018). "A decrease in the expression of ADAM-17 by silencing FoxM1 led to an inhibition of cell proliferation, tumor growth, and the production of tumor necrosis factor α." (PMID 29776401, 2018). "In our in vivo study, miRNA-370-3p plays a tumor-suppressive role, and this role is associated with the MGMT and FOXM1 downexpressions, while the expressions of TGFβ-RII and FOXO1 remain unchanged." (PMID 30497054, 2018). "Based on the published articles, the expression of FOXM1 is highly expressed in almost all malignancies and is closely related to tumour invasion and metastasis." (PMID 30250169, 2018). "Knockdown of miR-612 or overexpression of FOXM1 significantly reversed the tumor-suppressive activity of PAX8." (PMID 30021604, 2018). "Tumor sphere formation assay displayed that FoxM1 overexpressing cells form larger and more spheres compared with control cells." (PMID 30416986, 2018). "There was a statistically significant relationship between FoxM1 expression and histologic subtype (P = 0.042), clinical stage (P = 0.000), tumor recurrence (P = 0.040) and distant metastasis (P = 0.012)." (PMID 30416986, 2018). "In this study, we demonstrate that UBE2C is a transcriptional target of FOXM1 in ESCC, and likely present in several human neoplasias, thus further contributing to the loss of G2/M checkpoint control as a consequence of FOXM1 deregulation." (PMID 29596365, 2018). "Clinically, the level of miR-6868-5p was downregulated in CRC tissues and inversely correlated with microvessel density as well as levels of FOXM1 and IL-8 in tumor specimens." (PMID 30486864, 2018). "The results showed that FoxM1 was mainly expressed in the cell membrane and cytoplasm of tumor cells." (PMID 30580327, 2018). "Consistent with that finding was the IHC staining data showing a much stronger positive nuclear staining of FOXM1 in tumor samples generated from control Detroit 562 cells than from shp53 Detroit 562 cells." (PMID 29269868, 2018). "Our results identified a feedback loop of miR-6868-5p/FOXM1, in which miR-6868-5p inhibits tumor angiogenesis by suppressing FOXM1-IL-8 axis, and in turn FOXM1 downregulates miR-6868-5p by stimulating EZH2-mediated transcriptional suppression of miR-6868-5p." (PMID 30486864, 2018). "In the present study, we detected the protein expression of TNFa in tumor cell lysates and cell supernatants after FoxM1 was overexpressed or silenced." (PMID 29776401, 2018). "We also presented experimental evidence that strongly support the role of FoxM1 in tumor progression and metastasis of BC." (PMID 29707121, 2018). "FOXM1, a proliferation specific oncogenic transcription factor, was reported to regulate microtubule dynamics to mediate chemoresistance of tumor cells." (PMID 29435149, 2018). "In NPC tissues, FoxM1 correlated significantly with stem cells-related clinical pathological features including late clinical stage, tumor recurrence and distant metastasis." (PMID 30416986, 2018). "In this study, we showed that the expression of FoxM1 is correlated with that of HMGCR or SREBP2 in tumor tissues of HCC patients." (PMID 29765517, 2018). "The upregulation of FoxM1 and ADAM-17 led to an increase in the activities of cell proliferation and tumor growth, as well as TNFa expression and cleavage, whereas the downregulation of FoxM1 and ADAM-17 showed the opposite results." (PMID 29776401, 2018). "FoxM1 regulates cell cycle progression, proliferation, migration, metabolism, DNA damage response, angiogenesis, metastasis, and tumor development and progression." (PMID 29780443, 2018).
tumor (continued). "In summary, the findings from this study indicate that FoxM1 is significantly upregulated in ICC, and its overexpression is markedly associated with tumor progression and poor clinical outcomes in patients with ICC after hepatectomy." (PMID 30580327, 2018). "Overexpression of FoxM1 enhanced tumor proliferation, cell cycle progression, migration and stress fibers formation in vitro." (PMID 30416986, 2018). "FoxM1 was significantly upregulated in the tumor tissues compared with the non-tumor tissues, indicating FoxM1 was involved in the carcinogenesis of NPC (P < 0.01)." (PMID 30416986, 2018). "The mice in FoxM1 + sh-EGFP group were thinner than those in FoxM1 + sh-ADAM17 group 20 days after implanting the tumor." (PMID 29700308, 2018). "It has been shown that ectopic overexpression of FOXM1 can accelerate the development, proliferation, growth and survival of tumours in in vivo models." (PMID 29180117, 2018). "Higher levels of FOXM1 positive staining were found in PCI-13 shAMPKα1 tumor samples than in the control PCI-13 tumors." (PMID 29269868, 2018). "The results show that FoxM1 was markedly elevated in tumor tissues versus the paired peritumoral tissues." (PMID 30580327, 2018). "Accumulating evidence has demonstrated that FoxM1 can increase the invasive properties of tumor cells via matrix metalloproteinases (MMP) signaling pathway." (PMID 30416986, 2018). "In conclusion, our results show that FOXM1 seems to play a central role in ESCC carcinogenesis by upregulating many oncogenes found overexpressed in this tumor." (PMID 29682174, 2018). "The Cox regression proportional hazards model for multivariate analysis showed that tumor differentiation, resected margins, and the FoxM1 expression level were independent prognostic predictors for the OS of patients with ICC (all P < 0.05)." (PMID 30580327, 2018). "Using in vitro, together with in vivo experiments, we evaluated the therapeutic impact of the siFoxM1-Apt-CNBs combined with UMND transfection therapy and the expression of FoxM1 and E-cadherin in LNCaP cells and xenografts tumor in nude mice." (PMID 29313393, 2018). "FOXM1 has been reported to regulate tumor angiogenesis through promoting the transcription of angiogenic factors." (PMID 30486864, 2018). "The in vivo experiments in nude mice showed that knockdown of LOC653786 dramatically repressed xenograft tumor growth and FOXM1 expression." (PMID 29552295, 2018). "Clinical data available for both patients showed that despite similar tumor grade and stage as well as treatment received, the patient whose tumor expressed high levels of FOXM1 had a worse survival outcome." (PMID 30572639, 2018). "FOXO3, like FOXM1, is a forkhead transcription factor, a typical tumor suppressor and a functional antagonist of the oncogene FOXM1." (PMID 28482906, 2017). "But, an involvement of Rb in the FoxM1-mediated repression of these luminal differentiation genes is counterintuitive, as it is a tumor suppressor protein." (PMID 28387346, 2017). "Taken together these observations indicate that MuvB, B-MYB and FOXM1 contributes to tumor cell proliferation by activating the expression of mitotic genes." (PMID 28061449, 2017). "To examine consequences of FOXM1 expression in tumor cells in vivo, we employed an inducible, transgenic mouse model to express an activated FOXM1 transcript in urethane-induced benign lung adenomas." (PMID 29267283, 2017). "In this study, we found that FoxM1 expression was also elevated in CRC tumor tissues compared with the matched normal colorectal mucosa." (PMID 28148279, 2017).
tumor (continued). "Pearson correlation analysis showed that the level of FOXM1 was correlated with that of ABCC10 in tumor tissues (R2= 0.6158, p<0." (PMID 28051999, 2017). "Beyond altering tumor phenotype, we demonstrated that FOXM1 silencing conferred a greater sensitivity to standard first-line chemotherapeutic drugs, carboplatin and cisplatin, in our novel cellular models." (PMID 28482906, 2017). "Consistent with important role of FOXM1 and AGR2 in PIMAs, inactivation of either AGR2 or FOXM1 was sufficient to inhibit the tumor growth, invasion and metastasis in orthotopic mouse model." (PMID 29267283, 2017). "Our present data demonstrated that the knockdown of FOXM1 in tumor cells by RNAi reduced cell proliferation, migration, and invasion, suggesting that FOXM1 acts as an oncogene in RCC cells." (PMID 28902136, 2017). "We found that MYBL2 and FoxM1 expression had a close correlation with the tumor progression: both genes were higher expression in patients with advanced tumor stage than in normal tissues (*P < 0.05) and early-stage (*P < 0.05)." (PMID 28784180, 2017). "We found that transgenic expression of activated FoxM1-ΔN increased cell proliferation and tumor growth, findings consistent with the known role of FOXM1 in activation of cell cycle regulatory genes." (PMID 29267283, 2017). "Supporting our results, the expression of FoxM1 was dramatically increased in CRC tumor tissues compared to normal colorectal tissues." (PMID 28148279, 2017). "FOXM1 knockdown reduced tumour incidence, indicating that FOXM1 has a key role in tumour initiation." (PMID 28114286, 2017). "HM also upregulated miR-149-5p expression in colon tissues, whereas miR-149-5p functioned on the transcription factor FOXM1 to inhibit the migration of tumor cells in the colon." (PMID 28246536, 2017). "Since FOXM1 is required for KRAS/ERK signaling in mouse tumor models, our studies provide a rationale for pharmacological targeting FOXM1 in PIMA tumors with activating KRAS mutations." (PMID 29267283, 2017). "We used lentiviral shRNA to stably inhibit FOXM1 in A549 cells in an orthotopic xenograft tumor model." (PMID 29267283, 2017). "Our high throughput analyses revealed that FOXM1 gene was significantly up-regulated in both tumor subtypes." (PMID 28482906, 2017). "A higher iRAS in a tumor sample indicates that target genes of FOXM1 tend to have higher expression level and therefore a higher transcriptional activity of FOXM1 in this sample." (PMID 29100329, 2017). "This meta-analysis is the most comprehensive assessment of the literatures regarding FOXM1-protein expression and tumor prognosis to date." (PMID 28427178, 2017). "We analysed Kaplan-Meier overall survival (OS) curves according to the expression levels of dual strands of pre-miR-149 and FOXM1 and the relationships between FOXM1 expression and tumor stage and metastasis in ccRCC using the TCGA-KIRC database." (PMID 28902136, 2017). "Eventually, we knocked down endogenous Cath-D using its siRNA to elucidate the role of FOXM1 in inducing tumor development." (PMID 28978107, 2017). "To further figure out the function of FOXM1 in tumor invasion and metastasis, we detected migration and invasion of both cell lines using standard Matrigel chemoinvasion assays." (PMID 28978107, 2017). "SOX2, a marker of stem-like and less differentiated NSCLC tumor cells and a known transcriptional target of FOXM1, was increased in the epiFoxM1-ΔN tumors." (PMID 29267283, 2017). "Compared with shRNA-control group, FOXM1-silenced tumors had a decreased proliferative index and a significant reduction in tumor weight." (PMID 27351131, 2016). "Previous studies have shown that FoxM1 was essential for development of HCC, and overexpression of FoxM1 was associated with aggressive tumor features and poor prognosis." (PMID 27351282, 2016). "Using small interference RNA (siRNA), we then tested the involvement of FOXM1 in tumor progression and the acquisition of drug resistance." (PMID 27439614, 2016).